INS (insulin)
Diseases named in the same sentence as INS in open-access papers (continued):
Sharing a sentence is not in itself a finding about the gene and the disease.
hyperandrogenism (continued). "BAT transplantation could also significantly enhance endogenous BAT activity and increase the level of circulating adiponectin and insulin sensitivity, thereby eventually ameliorating hyperandrogenism, acyclicity polycystic ovaries and infertility in rats with PCOS." (PMID 35663310, 2022). "Effects of hyperandrogenism could be mediated via insulin and altered placental steroidogenesis." (PMID 36733795, 2022). "Therefore, elevated insulin can promote and exacerbate hyperandrogenism and PCOS symptoms." (PMID 36457554, 2022). "However, its phenotype is accompanied by a much wider range of reproductive (ovulatory dysfunction, polycystic ovarian morphology, infertility), endocrine (hyperandrogenism, disturbed gonadotropins level) and metabolic (glucose metabolism, insulin sensitivity, lipid profile) features." (PMID 33095902, 2021). "Overall, these findings suggest that hyperandrogenism may have a major impact on insulin sensitivity, although none of the PCOS diagnostic features per se are invariably associated with IR." (PMID 34071499, 2021). "Indeed, hyperandrogenism was found to induce an excessive release of insulin by pancreatic β-cells." (PMID 32917200, 2020). "Women with PCOS and anovulation, but with normal levels androgens, and those with hyperandrogenism but regular cycles, usually have normal insulin sensitivity and presumably do not have the same risk of IGT or type II diabetes as those with the “classical phenotype” of the syndrome." (PMID 27423183, 2016). "Mechanistic studies reveal their ability to regulate ovarian steroidogenesis, suppress pro-inflammatory cytokines, improve insulin sensitivity via the PI3K/Akt signaling pathway, and reduce hyperandrogenism by inhibiting 5α-reductase." (PMID 41268159, 2025). "Components of cow milk, such as casein, whey proteins, hormones, and growth factors, can elevate androgen receptor activity by increasing insulin and IGF-1 levels, leading to hyperandrogenism and potentially exacerbating HS symptoms." (PMID 39768986, 2024). "Elevated insulin levels also promote excessive ovarian androgen secretion and decrease the synthesis of SHBG in the liver, further exacerbating hyperandrogenism." (PMID 39351128, 2024). "Insulin and androgens restrict the liver from producing and releasing SHBG; thus, hyperandrogenism in people with PCOS results in low serum SHBG, which further increases testosterone levels." (PMID 38790905, 2024). "DMBG is a common insulin sensitizer that can control the blood sugar of type 2 diabetes, alleviate the clinical symptoms of PCOS patients, and reduce LH levels and hyperandrogenism." (PMID 37447160, 2023). "Also, PCOS women of the GG genotype had higher plasma insulin and HOMA-IR which was consistent with a study among the Kashmiri population, and findings by Sowers and colleagues, who had concluded a positive association of rs2414096 SNP of the CYP19 gene with hyperandrogenism in PCOS women." (PMID 37603197, 2023). "In line with the current literature, myo-Ins is a beneficial therapy to ameliorate insulin sensitivity, to improve the LH/FSH ratio, and to reduce the biochemical markers of hyperandrogenism." (PMID 37371854, 2023). "In addition, women with T1D or T2D exhibit a higher than typical incidence of hyperandrogenism (25%, 20%, respectively, compared to healthy women) and irregular menstrual cycles (24%, 18%), as key diagnostic criteria for PCOS, thus implicating exogenous insulin therapy in the pathogenesis of PCOS." (PMID 35269778, 2022). "In this scenario, hyperandrogenism related to PCOS can contribute to liver disease, promoting systemic inflammation, leading to decreased insulin sensitivity and hepatic fibrogenesis." (PMID 35576937, 2022). "Both follicular excess of androgens and increased levels of insulin downregulate aromatase in luteinized granulosa cells in PCOS women, contributing to the mechanism of a vicious cycle between inflammation, IR and hyperandrogenism." (PMID 36498989, 2022).
hyperandrogenism (continued). "Metformin activates AMPK, increases insulin sensitivity, decreases IGF-1 levels, lowers androgenic hormone levels from the adrenal glands and ovaries, improves ovarian and functional adrenal hyperandrogenism in PCOS, and prevents the development of acne." (PMID 33255783, 2020). "After 6 months of supplementation, melatonin significantly improved menstrual irregularities and biochemical hyperandrogenism in women with PCOS through a direct, insulin-independent effect on the ovary." (PMID 31139144, 2019). "FAI as the indicator of hyperandrogenism can serve as an indicator of glucose tolerance, as an increase in FAI is usually followed by increases in blood glucose concentration, insulin level, and glucose resistance." (PMID 30881692, 2019). "Both androgens and insulin inhibit SHBG secretion, increasing free and bioactive androgen levels and making clinical androgen excess worse." (PMID 27473078, 2017). "Characteristics of PCOS—ovulatory dysfunction, hyperandrogenism, abnormal ovarian morphology and endotoxinemia are reasonably connected with each other in this hypothesis, suggesting that imbalance of intestinal flora may be the co-activator of inflammation and insulin signaling pathway in PCOS." (PMID 26799617, 2016). "Mothers and sisters of PCOS probands exhibit menstrual irregularities, androgen excess, aberrant lipoprotein profiles, and MBS, with profound defects in insulin secretory function and sensitivity." (PMID 21899727, 2011). "Furthermore, via reducing insulin-mediated CYP17A1 activation in theca cells, overall improvements in insulin sensitivity directly alleviate ovarian androgen excess." (PMID 41596408, 2026). "In line with our previous studies, PCOS animals showed excess body weight gain/ovarian mass, abnormal metabolic indices (fasting insulin, blood glucose and HOMA-IR), androgen excess, multiple ovarian cysts, elevated AMH and leptin and decreased SHBG, adiponectin and 17-β estradiol." (PMID 38561673, 2024). "Insulin allows for ovarian androgen production and increases the levels of free testosterone, which results in the inhibition of SHBG and consequently plays a role in hyperandrogenism." (PMID 37062827, 2023). "Notably, due to the fact that insulin and HOMA-IR are closely correlated with androgens some authors suggested that IR was only particularly intense in PCOS patients with severe hyperandrogenism." (PMID 37432289, 2023). "Previous attempts, however, to employ exogenous insulin to induce hyperandrogenism in normal or PCOS women have not been particularly successful." (PMID 35269778, 2022). "Hence, not only the direct effects of insulin on androgens happen, but also disturbances in insulin-related pathways (PI3K, MAPK and MEK/ERK) are involved in androgen excess pattern in the IR- related- PCOS and NAFLD." (PMID 36419770, 2022). "Secondly, insulin decreases hepatic production of SHBG, the plasmatic carrier of sex steroids, thus increasing the amount of circulating free testosterone, which is responsible for the clinical signs of hyperandrogenism (hirsutism, acne and alopecia)." (PMID 34071499, 2021). "Considering this hypothesis, insulin could elevate androgen biosynthesis and reduce sex hormone-binding globulin (SHBG) which resulted in hyperandrogenism." (PMID 34362981, 2021). "The lifestyle intervention was not improved by the addition of herbal medicine for biochemical hyperandrogenism including testosterone, SHBG or FAI, gonadotropin hormones FSH or the FSH LH ratio, metabolic measurements of fasting glucose or insulin sensitivity or anthropometric hip‐to‐waist ratio." (PMID 28685911, 2017). "A meta-analysis of the published studies demonstrated that the use of insulin sensitizers does not reduce hyperandrogenism any better than OCPs." (PMID 27635134, 2016).
hyperandrogenism (continued). "Androgen excess in PCOS may involve the aggravation of metabolic abnormalities, such as increased visceral fat, decreased lipolysis in subcutaneous fat, insulin resistance in adipose tissue and skeletal muscle and lipid metabolism." (PMID 24901345, 2014). "In addition, they found that chronic exposure to insulin or DHT abnormally increased IRS1/IRS2 phosphorylation as well as GLUT1 and GLUT12 protein levels in hESC, suggesting that hyperandrogenism is also involved in influencing insulin signaling and glucose metabolism." (PMID 40410881, 2025). "For specific endometrial pathways, hyperandrogenism only plays a role in the presence of hyperinsulinemia, such as the impaired endometrial lipocalin signaling pathway, and DHT-enhanced up-regulation of prokineticin 1 (PROK1) in human embryonic stromal cells (hESC) only in combination with insulin." (PMID 40410881, 2025). "In addition to insulin, the anti-mullerian hormone (AMH), which is typically elevated in PCOS, also stimulates gonadotropin hormone-releasing hormone (GnRH) neurons, potentially promoting hyperandrogenism." (PMID 40650016, 2025). "Since EV treatment did not induce hyperandrogenism, this could be an explanation for the normal insulin sensitivity observed." (PMID 40563843, 2025). "Metformin (Met), a recognized insulin sensitizer, has been widely used for women with PCOS due to benefits, such as improving menstruation and hyperinsulinemia, hyperandrogenism, and abnormal metabolism, and it may also have a preventive effect on long-term cardiovascular diseases." (PMID 34407851, 2021). "Moreover, insulin, by lowering liver sex hormone–binding globulin (SHBG) production, increases androgen bioavailability at target organs, further contributing to clinical signs of hyperandrogenism." (PMID 32849300, 2020). "For example, a previous study reported that PAI-1 levels were increased in women with PCOS compared with control women, but detailed analysis found that insulin, HOMA index and BMI, and not androgen excess, were the variables actually associated with PAI-1 antigen levels." (PMID 31652917, 2019). "In particular, androgen excess in PCOS may contribute to increased visceral fat, decreased lipolysis in subcutaneous fat, reduced insulin sensitivity in adipose tissue and skeletal muscle, decreased HDL-C levels, and increased low-density lipoprotein cholesterol (LDL-C) levels." (PMID 24901345, 2014). "Furthermore, reports have indicated that rat skeletal muscle myotubes exposed to insulin and testosterone increase phosphorylation of Ser-636/639 residue in IRS-1, compared to the control condition, suggesting a link between IR and hyperandrogenism, both of which are present in PCOS-IR women." (PMID 22390153, 2012). "In this hierarchical cluster analysis, the authors showed that testosterone levels did not discriminate between these two phenotypes, which reinforces the idea that it may not be hyperandrogenism per se that discriminates between PCOS subtypes but that insulin plays a more dominant role." (PMID 37629271, 2023). "However, this does not rule out a role for insulin in adrenal androgen excess in women with PCOS." (PMID 37569402, 2023). "However, it has been recently put forward that hyperandrogenism, as well as being induced by insulin, may be directly induced by inflammation, regardless of the presence of IR." (PMID 29747700, 2018).
Autoimmunity (258 papers, 2004 to 2026). The occurrence of an immune reaction against the organism's own cells or tissues. "Various PTMs, including citrullination, oxidation, phosphorylation, acetylation, methylation, deamidation, and carbonylation, have been implicated in modulating T1DM autoimmunity, glucose regulation, and insulin metabolism." (PMID 40649891, 2025). "Despite the underlying autoimmunity, insulin secretion remains sufficient to maintain euglycemia, and patients are asymptomatic." (PMID 39860426, 2025). "Diversity and homeostasis of gut bacterial composition is highly associated with the pathogenesis of insulin dysfunction and type 1 diabetes melittus (T1D), hence emerged in parallel with the activation of autoimmunity." (PMID 38655301, 2024). "In T1D, maladaptive unfolded protein response (UPR) in insulin-producing β cells renders these cells susceptible to autoimmunity." (PMID 38889047, 2024). "It is known that the mechanism of T1DM is the destruction of insulin-producing β-cells in the pancreatic islets caused by autoimmunity, which contributes to insufficient insulin secretion." (PMID 35805493, 2022). "Antigen-specific tolerance induction to hybrid insulin peptides has the translational potential to preserve islet β-cells in new-onset or at-risk patients and prevent recurrent autoimmunity in transplant patients." (PMID 33673706, 2021). "The autoimmunity and insulin-deficient clusters were defined by high HbA1c at diagnosis, had higher risk for ketoacidosis and retinopathy, and progressed more rapidly onto insulin relative to the other clusters." (PMID 34110439, 2021). "When mice are forced to have only T cells expressing TCRs containing TRAV5D-4, approximately one percent of CD4 T cells becomes specific to an insulin B chain 9-23 peptide, and the mice are susceptible to develop anti-insulin autoimmunity." (PMID 34868047, 2021). "Type 1 diabetes (T1D) is an organ-specific autoimmune disorder caused by the destruction of insulin-producing pancreatic β-cells leading to an absolute insulin deficiency." (PMID 31365591, 2019). "Non-genetic factors are crucial in the pathogenesis of type 1 diabetes (T1D), a disease caused by autoimmunity against insulin-producing β-cells." (PMID 30718757, 2019). "It is possible to conclude that irisin hormone is not only associated with exercise but also with hormones, insulin resistance, inflammation and autoimmunity." (PMID 31881940, 2019). "Progression of islet cell destruction from autoimmunity leads to insulin therapy and associated complications of autoimmunity." (PMID 28819632, 2017). "Drug-induced diabetic models are similar to spontaneous type 1 DM models in terms of the loss of islets and deficiency of internal insulin, but the mechanism is different: the involvement of autoimmunity is a feature of the latter type." (PMID 23346100, 2012). "Recent clinical trials of antigen-specific or non-specific immune therapies have proved that modulation of islet specific autoimmunity in humans and prevention of insulin secretion loss in the short term after the onset of disease is achievable." (PMID 19046214, 2008). "The MHC class II, the CTLA4 and the PTPN22 loci have all been proved important in the pathogenesis of autoimmunity globally considered, whereas the insulin gene is a disease-specific T1D predisposition locus." (PMID 17697317, 2007). "Type 1 autoimmune diabetes is usually defined by a near-complete deficiency in insulin secretion due to the autoimmune destruction of beta cells, which is associated with the presence of anti-beta cell autoimmunity markers, particularly the autoantibodies directed to insulin, GAD, IA-2, and ZnT8." (PMID 40290321, 2025). "Since the repeat sample for these was obtained almost 6 months after insulin initiation, it may be a depiction of the underlying autoimmunity, although that remains unclear." (PMID 39027637, 2024).
Autoimmunity (continued). "DM in patients with TS is primarily caused by impaired insulin secretion due to autoimmunity or other reasons that are currently unknown." (PMID 38376731, 2024). "In addition, they should probably not be treated with sulfonylureas, they should be investigated for other forms of autoimmunity and they are at particular risk of hyperglycaemia and progression to insulin therapy." (PMID 31813006, 2020). "There is also a clear rationale to retrospectively analyse the interaction between HLA and treatment in other antigen-specific trials, especially where insulin has been used as the tolerising antigen given the association between insulin autoimmunity and HLA-DR4-DQ8." (PMID 32754804, 2020). "In animal beta cells, gluten peptides induce insulin secretion, an effect that is potentiated by palmitate, suggesting that gluten peptides may induce beta cell-stress, -dysfunction, -loss, and autoimmunity, and thus contribute to both T1D and T2D." (PMID 30428550, 2018). "Later theories, including the “accelerator hypothesis” and the “overload hypothesis” suggest that increased insulin resistance and insulin demand, as seen in, for example, obese individuals, cause beta cell stress and apoptosis and thereby induce autoimmunity." (PMID 28763444, 2017). "Autoimmune Addison’s disease (AAD) associates with exceptional susceptibility to develop other autoimmune conditions, including type 1 diabetes (T1D), marked by positive serum autoantibodies to insulin (IAA), glutamic acid decarboxylase (GADA) and insulinoma-associated protein 2 (IA-2A)." (PMID 26972575, 2016). "In the case of insulin, a target antigen in autoimmune diabetes, a low level of thymic expression, and so less thorough central deletion, corresponds to increased susceptibility to autoimmunity 15,16." (PMID 24684567, 2014). "These cells can also be generated in NOD mice and lead to a restoration of insulin production, demonstrating that they are resistant to autoimmunity." (PMID 41716816, 2026). "High plasma insulin obstructs efficient insulin signaling and rewires metabolic activity in autoimmunity." (PMID 42185247, 2026). "It is an autoimmune disorder characterized by the destruction of insulin-producing beta cells in the pancreas, resulting in lifelong dependence on exogenous insulin therapy." (PMID 41164034, 2025). "Our findings support BCL6 inhibition as a promising T1D immunotherapy, even after insulin autoimmunity is established in the B cell repertoire." (PMID 40909612, 2025). "Beyond its well-known role in sensing heat and pain, this channel influences how pancreatic cells produce insulin and how immune cells respond to stress, linking metabolic imbalance to autoimmunity." (PMID 41463571, 2025). "Immunosuppressive treatment and insulin therapy brought improvement, but the aggressive nature of autoimmunity and the need to intensify insulin therapy during steroid therapy significantly complicated the stabilization of the disease." (PMID 41169469, 2025). "Insulin autoantibodies (IAAs) are typically the first to appear during the pathogenesis of T1D, highlighting the pivotal role of insulin in initiating T1D autoimmunity." (PMID 41567805, 2025). "Further studies are needed to fully elucidate the mechanisms driving oxPTM generation of insulin, their variability in different pathological contexts, and their precise role in the transition from autoimmunity to beta-cell destruction." (PMID 40028329, 2025). "Type 1 diabetes (T1D) is a chronic hyperglycemia disorder emerging from beta-cell (insulin secreting cells of the pancreas) targeted autoimmunity." (PMID 40259265, 2025). "In diabetic NOD mice, TCR-like antibodies and CAR T cells expressing an insulin peptide/MHC class II TCRL antibody modulated autoimmunity." (PMID 39496501, 2025). "This provided the first serological evidence of autoimmunity against pancreatic islets, fundamentally challenging the insulin-centric view of disease pathogenesis." (PMID 40725617, 2025).